CXCR4 (C-X-C motif chemokine receptor 4)
Diseases named in the same sentence as CXCR4 in open-access papers (continued):
Sharing a sentence is not in itself a finding about the gene and the disease.
breast carcinoma (continued). "Thus CXCR4 overexpression did not override the dependency of these breast cancer cells on the EGF/CSF-1 paracrine loop for in vivo invasion." (PMID 22152016, 2011). "To investigate whether the differential E2-regulation of CXCR4 and CXCR7 could be extended to other breast cancer cell lines, we analyzed the expression of the components of the CXCL12 axis in ER-positive ZR-75 and ER-negative MDA-MB-231 breast cancer cell lines." (PMID 21695171, 2011). "We did not see an effect of CXCR4 expression on primary tumor growth as previously reported in other breast cancer models, suggesting that this effect might be cell line specific." (PMID 22152016, 2011). "Based on both the pattern of breast cancer risk in women with AIDS and the in vitro findings that CXCR4-tropic HIV induced apoptosis of breast cancer cells, we postulated that HIV strains tropic for CXCR4 may account for the reduction in breast cancer observed in HIV-infected women." (PMID 21179547, 2010). "In breast cancer, it has been found that secondary site tumor colonization during cancer metastasis is not random, but rather there is directed migration of CXCR4-expressing cancer cells towards the SDF-1 ligand at common secondary sites such as lungs and bone marrow." (PMID 20676220, 2010). "The foundation forour appreciation of the role that CXCR4 and CXCL12 may play in cancermetastasis was set in 2001, when a landmark study by Albert Zlotnik'sgroup demonstrated the importance of the CXCL12/CXCR4 axis in site-specificmetastasis of breast cancer." (PMID 18779872, 2008). "A number of GPCRs have been previously reported to be overexpressed in breast cancer, including CCR1, Opsin-3, CXCR4, PAR1, PAR2, EP2, EP4, GPR30 and the C3A anaphylatoxin chemotactic receptor, although whether any of these are regulated by RGS2 remains unknown." (PMID 18067675, 2007). "Notably, CXCR4 has been extensively studied, and several inhibitors targeting CXCR4, such as AMD3100 (Plerixafor), have been developed and tested in clinical trials, primarily for their role in mobilizing hematopoietic stem cells and in the treatment of cancers like leukemia and breast cancer." (PMID 41024311, 2025). "However, it has not yet been established whether CXCR4 is a potential target for imaging and therapy in breast cancer." (PMID 40075611, 2025). "In conclusion, our findings suggested that actein could inhibit breast cancer cells metastasis, which may act through the inhibition of EGFR/AKT and NF-κB signaling, suppressed cell adhesion to ECM proteins as well as the reduction of ECM degradation and CXCR4 expression." (PMID 30618758, 2018). "In the current study, we discussed whether platelet-derived growth factor receptor-α (PDGFRα) is required for SDF-1α/CXCR4 signaling and explored how NT21MP contributes to reversing CXCR4-induced EMT to provide insight into the potential efficacy of NT21MP as adjuvant chemotherapy for breast cancer." (PMID 28415580, 2017). "Blocking CXCR4 may attenuate breast cancer metastasis to regional lymph nodes and the lungs, and activation of CXCR4 is believed to be primarily ligand-dependent, as is supported by the antitumor efficacy of AMD 3100, an antagonist of chemokine (C-X-C motif) ligand 12 (CXCL12) binding." (PMID 22242160, 2012). "To assure that the effects of CXCR4 attenuation on breast cancer cell migration and invasion was not due to decreased cell viability resulted from the treatment with the CXCR4 blocking mAb or the CXCR4 antagonist; we assessed the effect of CXCR4 blockade on cell viability with an MTT assay." (PMID 20492653, 2010). "In other tumor entities, the results of phase I (breast cancer, NCT 01837095) and phase II studies (pancreatic cancer, NCT 04177810) are still pending, but at present, CXCR4 inhibitors have not met the expectations of clinical efficacy." (PMID 36982302, 2023).
breast carcinoma (continued). "CXCR4 inhibitors can impair tumor growth and metastatic dissemination in HER2 enriched breast cancer cells but do not reduce tumor growth, and can increase metastatic spread of triple negative breast cancer." (PMID 35754051, 2022). "We have previously demonstrated that it is the functional activation of both CXCR4 and CCR7, as opposed to their expression levels, that correlates with the invasive and metastatic phenotype of breast cancer cells." (PMID 34685420, 2021). "CXCR4 is known to be hypomethylated and overexpressed, while CXCL12 is hypermethylated and absent in breast cancer cell lines and primary tumors themselves." (PMID 34901003, 2021). "Furthermore, CXCR4-mediated targeting and TRAIL-mediated apoptosis induction in tumor cells suggests that ExoCXCR4+TRAIL may be used as an optional therapeutic tool, potentially providing a novel approach for advancing the treatment of brain metastases of breast cancer with anticancer agents." (PMID 32850457, 2020). "qPCR and flow cytometric analyses were carried out to assess CXCR4 and ACKR3 expression in four breast cancer cell lines, however none expressed both receptors at high levels." (PMID 30441765, 2018). "TQ was found to inhibit the expression of CXCR4 in MDA-MB-231 and MCF7 breast cancer cell lines, irrespective of the cell type and HER2 status." (PMID 30564115, 2018). "As a consequence, cytoplasmatic CXCR4 does not contribute to signal intensity in PET imaging, resulting in lower overall signal intensity of breast cancer cells than possibly assumed by in vitro examinations." (PMID 30191351, 2018). "In B cells and breast cancer cells CD24 excludes CXCR4, the receptor for Stromal Cell Derived Factor-1 (SDF-1), from lipid rafts whereas in the absence of CD24, CXCR4 can enter." (PMID 28083532, 2016). "In this experiment, down-regulation of CXCR4 expression were observed in all above cell lines, suggesting that the reduced expression of CXCR4 by TPD7 was irrespective of HER2 status in breast cancer." (PMID 25753200, 2015). "It is demonstrated that the Ahr-active omeprazole decreases invasion and metastasis in estrogen receptor (ER)-negative breast cancer cell lines by down-regulation of matrix metalloproteinase-9 (MMP-9) and C-X-C chemokine receptor 4 (CXCR4)." (PMID 26377202, 2015). "Although NCOA1 is known to promote breast cancer metastasis through working with multiple transcription factors to upregulate the expression of Twist1, ITGA5, CSF-1, SDF1 and CXCR4, the role of NCOA1 in breast tumor angiogenesis has not been investigated." (PMID 26287601, 2015). "A similar observation was made in a breast cancer lung metastasis model, where neither AMD3100, nor knock-down of CXCR4 led to increased survival." (PMID 25897429, 2015). "Furthermore, assessment of gene expression or intracellular cytoplasmic CXCR4 detection by flow cytometry could complement the analysis by IHC and indicate how CXCR4 and CXCL12 are behaving at the molecular level, deciphering the interface of this axis in the breast cancer pathobiology." (PMID 26161302, 2015). "On the other hand IGF-1 binds to the Gi coupled chemokine receptor type 4 (CXCR4) in the absence of Chemokine 12 (CXCL12), the natural ligand of CXCR4, to promote migration of breast cancer cells." (PMID 25356505, 2014). "Our results clearly indicate that plumbagin suppressed CXCR4 expression in both HER2-lacking and -overexpressing breast cancer cells, but had minimal effect on HER2 expression in BT474 breast cancer cells." (PMID 21880153, 2011). "The regulation of CXCR4 and CXCR7 by estrogens and their involvement in the E2-dependent growth of breast cancer cells, however, have not been well characterized." (PMID 21695171, 2011). "In summary, no clear-cut relationship between HER2/neu, CXCR4, SDF1, and metastasis and/or prognosis as obvious for breast cancer was found in ovarian cancer." (PMID 17245339, 2007).
breast carcinoma (continued). "Still, using a more sensitive technique, we did not detect a difference in CXCR4 and CXCL12 expressions between primary breast carcinomas and matching lymph node metastases." (PMID 16189523, 2005). "Therefore, because cytoplasmatic CXCR4 does not contribute to signal intensity in PET imaging, CXCR4-targeted PET imaging has a lower overall signal intensity of breast cancer cells than possibly assumed by in vitro examinations." (PMID 40075611, 2025). "In addition, in a previous study, the expression profiles of CXCL12/CXCR4/CXCR7 and CXCL13/CXCR5 in the positive and negative LNs of breast cancer patients were found." (PMID 40584290, 2025). "However, it is noteworthy, that although the (CK+/JUNB–/CXCR4–) phenotype was the most frequent in SCLC, none of the patients nor their CTCs had exclusively that phenotype, which was also the case in breast cancer DTCs." (PMID 36612166, 2022). "Therefore, these extensive experimental validations demonstrate that selective CXCR4 gain of function but not CXCR7 overexpression result in chemotherapy, especially paclitaxel resistance in breast cancer." (PMID 33966046, 2021). "With the exception of the MDA-MB-468 CXCR4 negative breast cancer cells, all other cell types (Jurkats, THP-1s, HUVECs, breast cancer cells (MCF-7, MCF-10A, MDA-MB-231 and 468 “CXCR4 knock ins”) had slight variations in surface receptor expression (within 3-fold)." (PMID 29682200, 2018). "The expression of three of these genes (CD163, CXCR4, THBS1) was found to predict relapse-free survival in a large, publically-available transcriptomic dataset generated from the tumors of patients with TNBC, but not other breast cancer subtypes." (PMID 30254632, 2018). "Thus, we first aimed to evaluate protein and mRNA expression levels of CXCR4 in non-tumorigenic breast epithelial cells, MCF-10A, and in two different human breast cancer cell lines by immunoblotting and qRT-PCR analyses." (PMID 27556298, 2016). "In breast cancer cells, it was reported that, unlike CXCR4, the expression of CXCR7 was suppressed by estrogen receptor-mediated signaling, leaving the question of how metastatic cancer cells up-regulate both CXCR4 and CXCR7 unanswered." (PMID 26413813, 2015). "Western blot and Flow Cytometry analysis revealed the same profile in 3 other breast cancer cell lines (MDA-MB361, MCF7 and T47D) and an absence of expression of CXCR4 or an absence of increase of this receptor upon co-culture with BMHC in two other one (Hs578T and SK-BR-3)." (PMID 26231656, 2015). "In addition, the NO donor DETA NONOate induced CXCR4 mRNA and cytoplasmic protein expression in the MDA-MB-231 and SK-BR-3 breast cancer cell lines." (PMID 19025611, 2008). "Our results confirm a univariate influence of HER2/neu expression on overall survival, which was completely independent of the expression of CXCR4 and the abundance of SDF-1, implying significant differences between the HER2/neu downstream pathways in ovarian cancer compared with breast cancer." (PMID 17245339, 2007). "The expression of C-X-C motif chemokine receptor 4 (CXCR4) is low or absent in normal tissues, while it is highly expressed in various types of cancer, including colorectal cancer, ovarian cancer, and breast cancer, and the CXCR4 level was inversely correlated with TTP expression." (PMID 30380668, 2018). "In addition, cats with CXCR4-positive mammary carcinomas showed lower serum SDF-1 levels then cats with CXCR4-negative mammary carcinomas (p=0.027), uncovering a putative negative feedback of the SDF-1 ligand on SDF-1/CXCR4 axis." (PMID 29285291, 2017).
breast carcinoma (continued). "One hypothesis is that these molecules occupy an allosteric site within CXCR4 not previously identified which does not interfere with CXCL12 or M1 signaling, but which may be partially required by CXCR4 and some as yet unidentified ligand to signal the intracellular milieu in breast cancer cells." (PMID 29682200, 2018).
prostate carcinoma (282 papers, 2006 to 2025). A carcinoma that arises from epithelial cells of the prostate gland. "High CXCR4 expression in prostate cancer cells is associated with their propensity to metastasize to the bone, a tissue that expresses a high level of the chemokine CXCL12." (PMID 36863017, 2023). "The CXCR4/CXCL12 axis appears to be tumor-promoting; increased expression of CXCR4 was linked to more aggressive behavior and metastasis in various tumor types, including prostate cancer." (PMID 36982302, 2023). "CXCR4 is the C-X-C 4 chemokine receptor, which was shown to be implicated in aggressive phenotypes in various types of cancer such as breast and prostate cancer." (PMID 37576552, 2023). "In prostate cancer patients, CXCR4 expression is significantly associated with a more aggressive disease, the presence of metastasis and poorer cancer-specific survival." (PMID 36140541, 2022). "In prostate cancer, CXCR4 upregulation is associated with poor prognosis and induces lymph node and bone metastasis." (PMID 35773731, 2022). "Meanwhile, miR-494-3 has been implicated as a regulator of CXCR4 not only in prostate cancer but also in many other tumors, including SS, according to previous bioinformatics and biological evidence." (PMID 36003502, 2022). "CXCR4 is a chemokine receptor commonly upregulated in several cancers including prostate cancers and, together with androgen receptors, has been implicated in the promotion of PCs progression." (PMID 33669559, 2021). "In prostate cancer, increased CXCR4 expression was strongly associated with cell migration, metalloproteinase expression, invasion, and bone metastasis." (PMID 34884984, 2021). "In prostate cancer, CXCR4 overexpression is associated with an aggressive phenotype and poor overall survival." (PMID 33096815, 2020). "CXCR4 has been implicated in tumor metastasis to distant organs via blood vessels in several tumor models, including melanoma metastasis to the lung, prostate cancer metastasis to the bone, and neuroblastoma metastasis to the bone marrow." (PMID 32635336, 2020). "The expression of CXCR4 protein is significantly associated with the presence of bone metastasis in prostate cancer." (PMID 32824865, 2020). "Another important cytokine that promotes CTCs homing is CXCL12, and the enhanced activation of the CXCL12/CXCR4 axis has been linked with prostate cancer metastasis." (PMID 32585812, 2020). "CXCL12 and its receptor CXCR4 are known as key regulators of highly migratory/invasive phenotype of prostate cancer and their expression is associated with metastatic disease and poor survival." (PMID 31718684, 2019). "In prostate cancer patients expression of chemokine receptors, such as CXCR4, is significantly associated with the presence of lymph node and bone metastasis and poor cancer-specific survival." (PMID 29221153, 2017). "Meta-analysis of studies of CXCR4 expression in multiple cancers including prostate cancer, non-small cell lung cancer, pancreatic ductal adenocarcinoma and others concluded that CXCR4 expression is associated with a poor prognosis and lower overall survival." (PMID 29088715, 2017). "Further studies are necessary to define the role of [68Ga]Pentixafor in prostate cancer imaging and its use for patients` risk stratification or monitoring of CXCR4 directed therapeutic approaches." (PMID 29221153, 2017). "In prostate cancer, CXCR4 expression is associated with higher tumor grade, and the use of a neutralizing antibody to CXCR4 limited the extent of bone metastases and growth of intraosseous prostate cancer cells after intratibial injections." (PMID 27618899, 2016). "CXCR4 expression is associated with shorter progression free survival in cancers, and in prostate cancers its expression is significantly associated with metastatic disease and poor survival." (PMID 27809841, 2016).
prostate carcinoma (continued). "Integrin can modulate tumor cell morphology, and regulate the expression of CXCR4 which is associated with the invasive phenotype and progression of prostate cancer." (PMID 24647809, 2014). "In contrast, overexpression of the chemokine receptors CCR4 and CXCR4 have been associated with poor prognosis and the promotion of a variety of cancers including prostate cancer." (PMID 24466240, 2014). "In summary, these data showed that PTEN loss-induced PI3K/Akt pathway induces CXCL12/CXCR4 expression, and this expression is particularly mediated by Akt kinase in both murine and human prostate cancer cells." (PMID 23902739, 2013). "The stromal derived factor-1 (SDF-1)/CXCR4 axis is associated with tumor aggressiveness and metastasis in prostate cancer." (PMID 24137439, 2013). "High expression levels of CXCR4 in human prostate cancers are associated with more frequent local recurrence and distant metastasis, suggesting that CXCR4 not only serves as a potential therapeutic target, but also a prognostic marker." (PMID 24259307, 2013). "An immunohistochemical study of human samples demonstrated that high NF-κB expression was associated with CXCR4 expression and that they are co-expressed in approximately one-third of patients with clinically localized prostate cancer." (PMID 24137439, 2013). "Taken together, these data define a relationship between PTEN loss and CXCL12/CXCR4 signaling in prostate cancer progression." (PMID 23902739, 2013). "Our results demonstrated that AMP had potent activities in inhibiting migration and invasion of prostate cancer cells in vitro and prostate cancer metastasis in the orthotopic prostate tumor animal model associated with downregulation of CXCR4 expression." (PMID 22693649, 2012). "Expression of CXCR4 is linked to the tendency of prostate cancer cells to metastasize to the bone, a tissue that expresses a high level of the chemokine CXCL12." (PMID 22359577, 2012). "Of note, radiotherapy strongly affected CTC count, causing their drastic decrease in twenty-four metastatic prostate cancer patients, while a CXCR4+ subpopulation of CTCs still persists up to three months upon treatment, suggesting their resistance to local radiotherapy." (PMID 39335650, 2024). "For prostate cancer, high CXCR4 levels were associated with worse cancer-related survival." (PMID 36672341, 2023). "The use of AMD3100, a CXCR4 partial agonist, also caused the mobilization of prostate cancer cells from the niche back into the circulation and may be therapeutically relevant." (PMID 29642534, 2018). "Interestingly, high levels of CXCR4 have been also observed in CD44+/CD133+ prostate cancer stem cells (CSC) and are associated with more frequent local recurrence and metastasis formation, suggesting a role of this receptor as a prognostic marker." (PMID 30591657, 2018). "As in primary bone tumours, expression of CXCR4 causes cancer progression, and, in the case of breast or prostate cancer, may increase the risk of metastasis to bone." (PMID 29098360, 2018). "Therefore PET/CT imaging targeting CXCR4 is a promising diagnostic approach potentially influencing future clinical management of advanced prostate cancer patients." (PMID 29221153, 2017). "These nuclear localized CXCR4 are functional and underlie the recurrence of prostate cancer." (PMID 25888629, 2015). "Emerging data highlight the significance of chemokine (C-X-C motif) ligand 12/chemokine (C-X-C motif) receptor 4 (CXCL12/CXCR4) signaling axis in the chemoresistance of several malignancies, including prostate cancer (PCa); however, underlying mechanisms remain largely elusive." (PMID 25359780, 2014). "Herein, we demonstrate that CXCR4 associated with the nucleus of malignant prostate cancer tissues." (PMID 23468933, 2013). "Similarly, Akt-mediated regulation of CXCR4 was observed in human prostate cancer cells with loss or mutation of PTEN." (PMID 23902739, 2013).